IGLV3-12 (immunoglobulin lambda variable 3-12)
Description:
V region of the variable domain of immunoglobulin light chains that participates in the antigen recognition. Immunoglobulins, also known as antibodies, are membrane-bound or secreted glycoproteins produced by B lymphocytes. In the recognition phase of humoral immunity, the membrane-bound immunoglobulins serve as receptors which, upon binding of a specific antigen, trigger the clonal expansion and differentiation of B lymphocytes into immunoglobulins-secreting plasma cells. Secreted immunoglobulins mediate the effector phase of humoral immunity, which results in the elimination of bound antigens. The antigen binding site is formed by the variable domain of one heavy chain, together with that of its associated light chain. Thus, each immunoglobulin has two antigen binding sites with remarkable affinity for a particular antigen. The variable domains are assembled by a process called V-(D)-J rearrangement and can then be subjected to somatic hypermutations which, after exposure to antigen and selection, allow affinity maturation for a particular antigen.
Synonyms: IGLV312; V2-8
Gene: Immunoglobulin variable (V) gene on chromosome 22 (22,771,824 to 22,772,582, forward strand). Ensembl gene ENSG00000211667.
Subcellular location: Secreted; Cell membrane
Gene Ontology:
Biological process: immune response
Cellular component: extracellular region; immunoglobulin complex; plasma membrane
Homologues: Paralogues in human: IGLV3-21 (86% identical), IGLV3-9 (86% identical), IGLV3-1 (71% identical), IGLV3-16 (68% identical), IGLV3-25 (68% identical), IGLV3-10 (66% identical), IGLV3-19 (63% identical), IGLV3-27 (63% identical), IGLV3-22 (62% identical), IGLV1-40 (61% identical), IGLV3-32 (61% identical), IGLV1-51 (57% identical), and 81 more.